IL4 (interleukin 4)
Diseases named in the same sentence as IL4 in open-access papers (continued):
Sharing a sentence is not in itself a finding about the gene and the disease.
cancer (continued). "There is a conspicuous association between IL-4-590C/T polymorphism and decreased risk of smoking-related cancer, particularly in Asians." (PMID 31871935, 2019). "The heterogeneity of IL-4-590C/T variant and smoking-related cancer was complicated by multiple indexes, so subgroup analysis of different ethnicities was carried out." (PMID 31871935, 2019). "In terms of originality, our meta-analysis is the first paper to study the relationship between IL-4-590C/T (rs2243250) polymorphism and smoking-related cancer." (PMID 31871935, 2019). "Cancer-specific survival was significantly associated with SNPs rs2243250 in IL4 and rs5275 in PTGS2, both of them remained significant after correction for multiple testing using the Benjamini-Hochberg method." (PMID 28117391, 2017). "An increased Th1/Th2 ratio (IL-2/IL-4) is associated with the activation of cell-mediated immunity and would be potentially beneficial for pathogen or cancer elimination, while a decreased ratio would raise the risk of inflammation progression." (PMID 27830496, 2016). "Even more surprising, there was a complete block in metastasis associated with cancer cell derived IL-4 expression." (PMID 27563494, 2015). "A rapidly growing number of epidemiologic studies have been conducted to investigate the effect of several IL-4 polymorphisms on human cancer risk." (PMID 25484626, 2014). "The Type II IL-4/IL-13 receptor has been found to be overexpressed in a variety of epithelial tumors, and treatment of cancer cell lines with IL-4 is associated with pro-proliferative and anti-apoptotic effects." (PMID 24672527, 2014). "As a critical anti-inflammatory cytokine, IL-4 has implicated in the pathogenesis of various cancers." (PMID 25484626, 2014). "More specifically, several polymorphisms of the gene encoding IL-4 have been proved to be risk factors for cancer." (PMID 25484626, 2014). "Previously, we have demonstrated that interleukin-4 receptor α (IL-4Rα) is overexpressed on a variety of human cancers and can serve as target for IL-4 immunotoxin comprised of IL-4 and a mutated Pseudomonas exotoxin." (PMID 25208941, 2014). "There was evidence that IL-4 -590C > T(rs2243250), −33 T > C(rs2070874) polymorphisms were associated with cancer risk." (PMID 25484626, 2014). "Polymorphisms of the IL4 gene have been associated with many cancers." (PMID 35565241, 2022). "Moreover, IL-4/IL-13 and their receptors have been also associated with apoptosis, chemosensitivity, and prognosis in various cancers." (PMID 33450900, 2021). "In addition, scRNA-seq revealed upregulation of several cancer-associated (Il-4/Il-13, Hsf1/HSP), oncogenic (TGFβ, NGF, FGF, MAPK) and self-renewal (Wnt, Notch) pathways in p63+/−;ErbB2 luminal cells and PIMECs per se." (PMID 34023861, 2021). "Gastrointestinal tract cancers are associated with IL-4 and IL-13 upregulation, which may facilitate cancer growth." (PMID 32512917, 2020). "In contrast to the anti-inflammatory role of PPARγ in IL-4-polarized macrophages, the enhanced PPARγ signalling in cancer-associated PMN-MDSCs decreases the lysosomal acid lipase (LAL), generating reduced ROS production and impairing cancer cell proliferation and metastasis." (PMID 32823961, 2020). "Some meta-analyses have indicated that IL-4 rs2070874 may be associated with cancer development in Asian populations." (PMID 32744314, 2020). "Potential effect of IL-4 and IL-13 (250 ng/mL, 24 h) on the expression of genes encoding proteins relevant for cancer development by facilitating angiogenesis (HIF1A and VEGFA), inflammation (PTGS2, NOS2, CCL2), and metabolic reprogramming (GLUT1, ODC1, NOS2) was evaluated." (PMID 32512917, 2020). "Moreover, in favor of its cancer-supporting role, IL-4 elevation has been directly linked with higher mortality." (PMID 32512917, 2020). "However, any association between smoking-related cancer risk and IL-4-590C/T variant was found in Caucasians." (PMID 31871935, 2019).
cancer (continued). "Like IL-6, it has been shown that the expression of IL-4 and IL-10 is associated with cancer 87-89." (PMID 31602271, 2019). "Based on it, the study intends to clarify whether IL-4-590C/T variant increases the risk of smoking-related cancer through meta-analysis." (PMID 31871935, 2019). "Subgroup analysis by ethnicity showed that the IL-4-590C/T polymorphism was associated with a decreased risk of smoking-related cancer in the Asian population (CT vs. TT: P=0.008, OR = 0.878, 95% CI: 0.798–0.967; CC + CT vs. TT: P=0.030, OR = 0.903, 95% CI: 0.824–0.990)." (PMID 31871935, 2019). "However, in order to determine a comprehensive conclusion on the correlation between smoking-related cancer susceptibility and IL-4-590C/T polymorphism, more prospective cohort studies are still needed in the future." (PMID 31871935, 2019). "Therefore, there is a need for more multicentric researches with large samples to be carried out in future to gain more insights into the association between IL-4 rs2243250 polymorphism and smoking-related cancer." (PMID 31871935, 2019). "The 95% confidence interval (95% CI) and its odds ratio (OR) were adopted to access the relation between IL-4-590C/T gene polymorphism and smoking-related cancer; sensitivity analysis and publication bias assessment were carried out after the studies' quality evaluation." (PMID 31871935, 2019). "The effect of TDB on the two macrophage phenotypes is substantial, with TDB enhancing the M1‐like phenotype of GM‐CSF macrophages and down‐regulating M2‐like markers commonly associated with TAMs and cancer progression 31, 47, 48 for both GM‐CSF and M‐CSF/IL‐4 BMMs." (PMID 28722316, 2017). "Second, most of the studies included in the present meta-analysis only focused on the relationship between IL-4 intron 3 VNTR polymorphism and cancer risk, which made it hard to assess the effects of IL-4 haplotypes composed of different IL-4 polymorphisms on carcinogenesis." (PMID 25484626, 2014). "The expression of periostin is stimulated in pathological states by a wide range of factors, including interleukin 4 and 13, transforming growth factor beta, angiotensin 2, bone morphogenic protein 2, connective tissue growth factor 2, mechanical stretch, and several cancer-associated mediators." (PMID 40053143, 2025). "IL-4 intron 3 VNTR polymorphism could influence the risk of human cancer." (PMID 25484626, 2014). "Thus our result implicated that [AP1-V12]6 might inhibit IL-4 mediated cancer cells proliferation probably by binding the IL-4 receptor expressed on cancer cells." (PMID 24339977, 2013). "Specifically, we observed a significant decrease in the levels of MIP-1α, GM-CSF, IL-13, IL-6, IL-10, IL-5, IL-12p70, and IL-4 after SNS administration, all of which are associated with the severity of MMD symptoms and cancer prognosis." (PMID 41491244, 2026). "DSPS can promote the proliferation of T lymphocytes in cancer patients by regulating the expression of cytokines (such as IL-2, IL-4, IL-6, IFN-γ)." (PMID 40867887, 2025). "Despite limited research on the molecular pathways in these anti-atherotrombotic processes, butyrate seems to prevent EP4 overactivation through homeostasis, Interleukin-4 (IL-4), inflammation, and cancer connections." (PMID 41516038, 2025). "IL-4 is a typical immunomodulatory cytokine that is of considerable importance in immune regulation, allergic responses, and cancer therapy." (PMID 39910524, 2025). "IL-4 and IL-13 play important roles in Th2 immune responses, metabolism, tissue regeneration, remodeling, cancer, learning, and memory." (PMID 40405976, 2025). "When exposed to LPS, microglia display heightened glycolytic activity, akin to the Warburg effect observed in cancer cells, while anti-inflammatory IL-4 treatment triggers a reduction in glucose uptake and lactate production." (PMID 39828750, 2025).
cancer (continued). "In the TME of PC, IL-4 levels are elevated, promoting cancer cell growth and acting as an immunosuppressive factor, thereby limiting the effectiveness of immunotherapy." (PMID 39958351, 2025). "The activation of IL4 expression in the cancer compartment in PNI is supported by a previous report that the PNI microenvironment was associated with decreased CD8+ T and Th1 cells and increased Th2 cells." (PMID 40075699, 2025). "Specifically, Th2 cells promote cancer cell proliferation by secreting cytokines, such as IL-4 and IL-10, driving macrophage differentiation to the M2 phenotype." (PMID 40801655, 2025). "Given the role of IL-4, its attenuation following RS indicates a more favorable perioperative immune profile, potentially limiting cancer-cell survival and spread." (PMID 41155334, 2025). "We also identify local IL-4 produced by intratumor myeloid cells as a critical factor inducing TAP2 downregulation in cancer cells and mediating reduced sensitivity to PD-1 axis blockers." (PMID 40091029, 2025). "Our results indicate that IL4 and possibly other factors secreted by Py230 cancer cells upregulate VISTA expression on macrophages." (PMID 40316725, 2025). "IL-4 signaling promotes protumorigenic myelopoiesis, driving non-small cell lung cancer, and blockade of IL-4R signaling enhanced cancer immunotherapy." (PMID 39744952, 2025). "As cytokines involved in cancer progression, neutralizing inhibitors targeting IL-1, IL-4, TGFβ, and IL-10 have shown the potential to improve cancer." (PMID 41341593, 2025). "Currently, CAR-T technology has proven effective in overcoming IL-4-induced immunosuppression and has become a promising option for cancer treatment." (PMID 39958351, 2025). "Specifically, it has been described that the interleukin-4 (IL4)-mediated cellular response requires PARP14 activity on STAT6 to bind to the target promoters of the IL4-mediated inflammatory cascade in cancer, inflammation, and immune response." (PMID 41463260, 2025). "Th1 cells producing IFN-γ exhibit anti-cancer properties, while Th2 cells generating IL-10 and IL-4 support the humoral immune-response." (PMID 40403026, 2025). "IL-4 facilitates cancer-cell migration, epithelial–mesenchymal transition, and immune evasion, and its blocking has been shown to improve the effectiveness of cancer immunotherapy." (PMID 41155334, 2025). "The shift from M1 to M2 is orchestrated by interleukins IL-4 and IL-13, secreted by various cells within the cancer ecosystem, including cancer cells themselves." (PMID 39676864, 2024). "In contrast, mice deficient in IL-4R in the granulocyte-monocyte progenitors exhibited poorer cancer growth than wild-type mice and had much smaller numbers of mo-mac in cancer, suggesting that IL-4 signaling is a prerequisite for the development of MDCSs." (PMID 38474078, 2024). "Treatment with a neutralizing anti-IL-4 mAb inhibited cancer growth in the cancer-bearing mice and the genetic mouse model." (PMID 38474078, 2024). "Conversely, M2 type TAMs, are characterised by CD206 and CD163, and activated by interleukin-4 (IL-4), IL-13 and periostin (secreted by cancer stem cells [CSCs] and CAFs)." (PMID 39851940, 2024). "Mice selectively deficient in the IL-4 receptor I in tissue-resident macrophages showed cancer growth comparable to that in wild-type mice, suggesting the indispensable role of tissue-resident macrophages IL-4 signaling in cancer expansion." (PMID 38474078, 2024). "The work presented here was conducted in vitro, and there is a need for further investigations using in vivo models to provide a better understanding of the varied roles of IL4 signaling and its contribution to cancer progression." (PMID 38731867, 2024). "The reduction of the anti-inflammatory cytokine IL-4 and the elevation of the pro-inflammatory factors L-6 and IL-8 in EC contributed to understand the intricate relationship between inflammation and cancer." (PMID 38464838, 2024).
cancer (continued). "Although associations have been identified between IL-4, IL-6, IL-8, IL-10, IL-1β, TNF-α, COMT, CLOCK, PER, and 5-HTTLPR-related genes and cancer-related fatigue, the relationship between IL-6 and cancer-related fatigue remains controversial." (PMID 39372868, 2024). "In the context of cancer, IL4 signaling has largely been studied for its effects on immune cells that drive cancer progression." (PMID 38731867, 2024). "In turn, IL-4 promotes cancer metastasis and stimulates macrophages to release epidermal growth factor." (PMID 39409110, 2024). "Depletion of cholesterol from TAMs increases sensitivity to IL4 and promotes polarization to M2-like macrophages to support cancer progression." (PMID 37872251, 2024). "BCL2 is a known target of IL4 signaling and an important regulator of apoptosis that has become a target of interest in several cancers." (PMID 38731867, 2024). "The media in the BMDMs was replaced by CM generated from PanAsc 2159 cancer cells or media containing IL-4." (PMID 39337472, 2024). "BCL-2 family proteins have been identified as targets for cancer therapy, and their expression has been shown to be induced by IL4 in lymphocytes." (PMID 38731867, 2024). "A future goal is to systematically characterize epigenetic changes that occur downstream of IL4/IL13 signaling in cancer cells." (PMID 38731867, 2024). "Metavert treatment further downregulates procancer cytokines like IL-6 and IL-4, induces cancer cell apoptosis, and attenuates the expression of cancer stem cell markers, as well as impedes cancer growth and metastases." (PMID 37444617, 2023). "The increase in CX3CL1 chemokine levels can be attributed to the interaction of 4T1/GFP cancer cells with IL-4." (PMID 37445941, 2023). "For example, lesion cells produce IL-13, and PSC and cancer cells can produce IL-4, both factors that drive M1 to M2 polarization." (PMID 37638028, 2023). "Interleukin-4 (IL-4) and its receptors (IL-4R) are crucial in cancer cell proliferation and other biological behaviors like migration and invasion." (PMID 37117331, 2023). "Here, the activators for both M1 (LPS) and M2 (cancer supernatants and IL-4) and BAM15 (a synthetic mitochondrial uncoupling agent) reduced mitochondrial energy, perhaps to initiate specific responses." (PMID 38140036, 2023). "Altogether, this information supports that IL‐4 upregulation and consequently IL4I1 secretion represent a real hallmark of mregDCs, explaining their detrimental role in cancer progression and resistance." (PMID 38117000, 2023). "Th1 and Th9 cells in the TME boost CD8+ T cells’ ability to fight tumors, mainly by secreting IL-4 and IFN-γ, which are linked to a favorable prognosis in various cancer types." (PMID 37513975, 2023). "Secreted inflammatory cytokines in cancer cells, including IL-22, IL-6, IL-8, IL-4, IL-1β, HGF, IGF-1, EGF, G-CSF, TNF-α, VEGF, and IL-11, can confer the promotion of chemo- and radioresistance." (PMID 38140352, 2023). "In contrast, M2 stimulates angiogenesis, tissue healing, and cancer-cell proliferation by secreting anti-inflammatory cytokines such as IL-4, IL-1, and VEGF." (PMID 37513975, 2023). "Type 2 immunity play a role in cancer initiation and progression, type 2 cytokines (e.g., IL-4 and IL-13) can inhibit the function of cytotoxic T cells, which limit the ability of T cell to eliminate cancer cells." (PMID 37925492, 2023). "Increased levels of circulating IL-1 (cancer-promoting), IL-2, IL-2 receptors (IL-2R) (cancer-suppressive), IL-4, IL-8, IL-17 (cancer-promoting) and TNF-α have been reported in patients with SSc." (PMID 37681925, 2023). "For the cancer treatment study, IL-4 levels in the double and triple combination treatments significantly decreased compared to those in the control and vehicle groups." (PMID 37238871, 2023).
cancer (continued). "At this stage it is also likely that the phenotype of M2 macrophages is additionally controlled by CD4+ T helper type 2 (Th2) cells that express IL-4 and IL-13, and counteract the Th1 cell responses, as observed in other cancers." (PMID 37638028, 2023). "Our own studies confirm the influence of cytokines (i.e., concentrations of IL-1A, IL-1B, IL-2, IL-6, IL-10, TNF, and IL-4) on the emergence of fatigue in all its dimensions in patients with cancers of the reproductive organs at various stages of treatment." (PMID 36834426, 2023). "Interleukin-4 (IL-4) is an anti-inflammatory and immunomodulatory cytokine that promotes cancer-directed immune surveillance." (PMID 37176567, 2023). "In both cancer patients and non-cancer-afflicted subjects, IL-4, IL-5, IL-12p70, IL-17, IFN-α, and TNF-α all trended to significantly decrease at the early stage and markedly increase at the late stage of Omicron infection." (PMID 37035158, 2023). "Cancer cells cultured with macrophage activation factors (IFNγ/Pam3SCK4, or IL-4) change their chemokine profile." (PMID 37445941, 2023). "IL-6 has been found to stimulate a macrophage phenotype change that promotes cancer by regulating the level of receptors for IL-4." (PMID 37760608, 2023). "In this study, human monocytes (THP-1 cells) were differentiated with phorbol 12-myristate 13-acetate (PMA) into macrophages before the induction of M1 polarization by LPS and M2 macrophages using IL-4 and cancer cell supernatants." (PMID 38140036, 2023). "Increased levels of CX3CL1 (from 75 to 115 pg/mL, p = 0.0056) and CCL11 (from 13 to 20 pg/mL, p = 0.0077) were also observed in S + M2, which can be explained by the interaction of 4T1/GFP cancer cells with the M2 activation factor IL-4." (PMID 37445941, 2023). "The Th2 cytokine interleukin 4 (IL4) promotes macrophage differentiation into alternative subtypes and plays important roles in physiology, in metabolic and inflammatory diseases, in cancer and in tissue regeneration." (PMID 36610795, 2023). "IL-4 expressed by Th2 cells contributed to cancer cell proliferation, epithelial-mesenchymal transition and metastasis." (PMID 37370746, 2023). "Babaei E. and colleagues revealed a significant decrease in IL-4 production in mice with cancer receiving dendrosomal curcumin." (PMID 35011106, 2022). "Several clinical studies have found high circulating levels of IL-4 in patients with various types of cancer, as well as a decrease in its levels in patients with complete response following neoadjuvant chemotherapy." (PMID 36552602, 2022). "New media free of treatment and cytokines was replaced for an additional 24 h to exclude ferrichrome or IL-4 direct effect on cancer cells." (PMID 36333531, 2022). "Prior studies indicated an association between interleukin 4 (IL-4) and cytotoxic T lymphocyte protein 4 (CTLA-4) gene polymorphisms in many types of cancers, including HCC that are either hepatitis B virus (HBV)- or hepatitis C Virus (HCV)-induced." (PMID 35525950, 2022). "It seems equally possible that basophil-derived IL-4/IL-13 also favor tumorigenesis by diminishing Th1-like immunity that is better suited to contest the cancer." (PMID 36578500, 2022). "Ferrichrome treatment of cancer cells significantly (P < 0.001) reduced cancer cell migration and invasion as compared to IL4-CM treatment." (PMID 36333531, 2022). "Specifically, IL-4 and IL-13 have demonstrated induction of cancer apoptosis as well as anti-inflammatory and innate immune activation functions." (PMID 35924165, 2022). "IL-4 is a multifunctional cytokine that plays a critical role in the regulation of host antitumor immunity in diverse types of cancers." (PMID 36466926, 2022).